RPSA (ribosomal protein SA)
Diseases named in the same sentence as RPSA in open-access papers (continued):
Sharing a sentence is not in itself a finding about the gene and the disease.
glioma (4 papers, 2020 to 2024). A benign or malignant brain and spinal cord tumor that arises from glial cells (astrocytes, oligodendrocytes, ependymal cells). "In contrast, the higher expression of FRAT1 and RPSA in gliomas is associated with better survival and delayed tumor recurrence." (PMID 38672212, 2024). "In our study, the overexpression of RPs, such as RPSA, RPL18A, RPL19, and RPS12, was associated with a better prognosis in patients with glioma." (PMID 38672212, 2024). "Four drugs (Puromycin targeting RPL8; Doxorubicin, Daunorubicin, Mitoxantrone targeting RPSA) were identified as potential drug candidates with antineoplastic activities and played the vital role in Glioma therapy." (PMID 33635875, 2021). "The inhibition of 37LRP, a precursor of RPSA, represses glioma growth and invasion, and the resulting downregulation of RPSA suppresses p-ERK1/2 and p-p38 in U251 cells, suggesting the inhibitory effect of RPSA on glioma tumorigenesis." (PMID 32964027, 2020). "The expression of four genes (CER1, FRAT1, FSTL1, and RPSA) involved in the Wnt/β-catenin pathway was significantly associated with mortality and disease progression in patients with glioma, especially in those with grade III glioma." (PMID 38672212, 2024). "Downregulated genes in glioma neurospheres, RPL and RPS families (RPLP1, RPSA and others), are indexed in the GO term “translation” (GO:0006412), as well as in the “KEGG 2021 Human Ribosome” libraries." (PMID 36231068, 2022).
meningitis (4 papers, 2020 to 2024). A disorder characterized by acute inflammation of the meninges of the brain and/or spinal cord. "This study provides a greater understanding of the novel functions of the host-interactional molecule RPSA and the pathogenic role of bacterial Eno in meningitis, and it forms the basis for new therapeutic strategies to treat meningitis." (PMID 33618766, 2021). "Additionally, RPSA is ubiquitously expressed across various cell types and has been reported as a cell receptor for infectious agents that cause meningitis, including, but not limited to, Neisseria meningitis, Streptococcus pneumoniae, Haemophilus influenzae, and Escherichia coli." (PMID 33603733, 2020). "Passive protection of mice with anti-Eno antibody increased survival, indicating that Eno-RPSA interaction is important for SS2 meningitis." (PMID 33618766, 2021). "Therefore, in studying the pathogenesis of SS2-induced meningitis, it is essential that we explore the functions of RPSA+ PMNs and their effects on the BBB." (PMID 33603733, 2020). "To investigate whether PMNs infiltrate the brain tissues of mice with SS2-induced meningitis, we determined the PMN and RPSA+ PMN counts in brain homogenates of mice with SS2-induced meningitis via flow cytometry." (PMID 33603733, 2020). "RPSA has been reported to mediate disruption of the BBB by various meningitis-inducing bacteria." (PMID 33603733, 2020). "Ribosomal protein SA (RPSA) of human brain microvascular endothelial cells (HBMECs) can transfer from the cytosol to the cell surface and act as a receptor for some pathogens, including Streptococcus suis serotype 2 (SS2), a zoonotic pathogen causing meningitis in pigs and humans." (PMID 38331785, 2024). "Thus our study increases our understanding of the pathogenesis of SS2, and may provide a novel strategy of meningitis control, for example, through blocking the interaction of Eno with RPSA and inhibition of apoptosis." (PMID 33618766, 2021). "We had previously found that S. suis serovar 2 Eno, as a virulence factor involving meningitis, promotes HSPD1 expression in PBMECs by targeting RPSA, which in turn induced apoptosis, hurting the BBB integrality." (PMID 35805155, 2022). "This study reveals novel functions for the host-interactional molecules RPSA and HSPD1 in BBB integrity, and provides insight for new therapeutic strategies in meningitis." (PMID 33618766, 2021).
esophageal cancer (3 papers, 2020 to 2022). A primary or metastatic malignant neoplasm involving the esophagus. "In breast and esophageal cancer, RPSA is associated with the suppression of apoptosis and autophagy." (PMID 36293493, 2022).
gastric cancer (3 papers, 2020 to 2023). A primary or metastatic malignant neoplasm involving the stomach. "RPSA positively regulates expressions of UPA and MMP-9 in gastric cancer, which is vital for the tumor matrix and basement membrane." (PMID 32964027, 2020).
ZIKV infection (3 papers, 2021 to 2025). "The intracellular domain (1–85 AA) of RPSA has recently been shown to bind to the membrane-bound E protein of Zika virus (ZIKV) to reduce the ubiquitination of the E protein in a way that attracts the de-ubiquitination enzyme EIF3S5, preventing ZIKV infection." (PMID 38331785, 2024).
bacterial meningitis (2 papers, 2020). Inflammation of the membranes surrounding the brain and spinal cord due to a bacterial infection. "Several persons with RPSA mutation in these pedigrees developed bacterial meningitis or pneumonia, suggesting that persons with intestinal varices should be examined for the presence of a functional spleen." (PMID 31498527, 2020). "As a receptor for virulence factors of these bacteria, RPSA enables bacteria to infiltrate the BBB by facilitating entry into cells or by eliciting disruption of the BBB by inducing apoptosis, thereby allowing invasion of brain tissues and, subsequently, bacterial meningitis." (PMID 33603733, 2020).
hypertrophic cardiomyopathy (2 papers, 2024). A condition in which the myocardium is hypertrophied without an obvious cause. "Finally, we examined the distribution and expression of RPSA in adult hypertrophic Mybpc3c.2373InsG mice, which are homozygous for the hypertrophic cardiomyopathy Dutch founder mutation." (PMID 38743494, 2024).
arthropathy (1 paper, 2024). Any disorder of the joints. "In the colon, it is suggestive that the increased expression of KRAS and RPSA are correlated with a higher risk of UC with arthropathy (OR 1.555, 95%CI 1.134–2.132; OR 2.057, 95%CI 1.161–3.646, respectively)." (PMID 38302916, 2024). "IVW-MR analysis also found evidence for the casual association between MTOR, ARNTL, KRAS, and RPSA with UC along with arthropathy ((OR 0.334, 95%CI 0.239–0.467; OR 0.607, 95%CI 0.499–0.739; OR 1.537, 95%CI 1.927–1.980; OR 1.756, 95%CI 1.133–2.724, respectively)." (PMID 38302916, 2024).
atherosclerosis (1 paper, 2021). A disease characterized by the build-up of fatty material and calcium deposition in the arterial wall resulting in partial or complete occlusion of the arterial lumen. "Alternatively, during atherosclerosis, more prominent self-antigens (i.e., RPSA) are released to hijack the immune response and drive the generation of high-affinity auto-antibodies." (PMID 34305930, 2021).
brain injuries (1 paper, 2020). "A previous study on the mechanism of microglial activation following nervous system injuries found that upregulation of RPSA expression on the surface of microglia following brain injuries may activate microglia and promote its migration to the brain tissues, thereby causing damage to brain tissues." (PMID 33603733, 2020).
cardiomyopathy (1 paper, 2025). A disease of the heart muscle or myocardium proper. "Importantly, impaired RPSA increases cardiomyopathy and in cardiomyocyte degeneration, as new cardiomyocytes lose their structure in the absence of laminin." (PMID 39641799, 2025).
co-infection (1 paper, 2018). "These functions provide clues about the theoretical consequences that the sequestering of RPSA and RPS29 by the CRE might entail, such as avoiding co-infection with other members of the Flaviviridae family or the induction of hepatocarcinoma." (PMID 30382192, 2018).
colon carcinoma (1 paper, 2018). "RPSA (also name as laminin receptor 1) transcript was shown to being higher in colon carcinoma tissue." (PMID 29876008, 2018).
colorectal adenocarcinoma (1 paper, 2025). The most common type of colorectal carcinoma. "The primary colorectal adenocarcinoma tissues and corresponding resection margins showed an overexpression of both RPSA and 67EBP at the protein level in the CRC tissues." (PMID 40141206, 2025).
colorectal tumors (1 paper, 2025). "The expression of RPSA in colorectal tumors and normal mucosa corresponding to the resection margins was evaluated by indirect immunofluorescence on cryosections using an anti-RPSA antibody." (PMID 40141206, 2025).
dilated cardiomyopathy (1 paper, 2024). Cardiomyopathy which is characterized by dilation and contractile dysfunction of the left and right ventricles. "The loss of RPSA causes the ribosomes and translation to lose their sarcomeric localization, eventually leading to dilated cardiomyopathy." (PMID 38743494, 2024). "These genetic mosaic mice with Rpsa knockout in a subset of cardiomyocytes developed dilated cardiomyopathy, featuring atrophy of RPSA-deficient cardiomyocytes, compensatory hypertrophy of unaffected cardiomyocytes, left ventricular dilation, and impaired contractile function." (PMID 38743494, 2024).
immunodeficiency disease (1 paper, 2020). Disease in which there is a deficiency or defect in the mechanisms of immunity, either cellular or humoral. "Similarly, the genotypability of RPSA (associated with the immunodeficiency disease Isolated congenital asplenia – OMIM 271400 –) improved from 63.29% to 100%, and that of the tumor suppressor gene PTEN improved from 78.55% to 100%." (PMID 32523024, 2020).
insulinoma (1 paper, 2015). "Western blotting for the ribosomal small subunit proteins RPS9 and RPSA in cytosolic and membranous fractions from glucose-stimulated floxed Ire1αFe/Fe insulinoma cells indicated Ire1α deletion in vitro disrupted glucose-stimulated recruitment of the ribosome to the membranous fraction." (PMID 26469762, 2015). "The increased monosomes detected in islets and the IRE1α-deleted insulinoma line were accompanied by basally increased RPS9 and RPSA protein, but not increased mRNA levels." (PMID 26469762, 2015).
ischemia (1 paper, 2025). A hypoperfusion of the BLOOD through an organ or tissue caused by a PATHOLOGIC CONSTRICTION or obstruction of its BLOOD VESSELS, or an absence of BLOOD CIRCULATION. "Importantly, the EATDS-derived exosomes have been unveiled for their potential cardiac responses and our previous findings identified major ribosomal proteins including RPL10A, RPL14, RPL30, RPS18, FAU-40 (RPS30), and RPSA (Laminin Receptor, LR) in the vesicles of ischemia-challenged EATDS." (PMID 39641799, 2025). "The expression of RPL10A, RPL14, RPL30, RPS18, FAU-40 (RPS30), and RPSA (Laminin Receptor, LR) was assessed in the myocardial and EAT tissues of MI, CABG and HL swine models and in LVSCs and EATDS challenged with ischemia." (PMID 39641799, 2025).
lung adenocarcinoma (1 paper, 2016). A carcinoma that arises from the lung and is characterized by the presence of malignant glandular epithelial cells. "RPSA encodes a ribosomal entry protein known to be up-regulated in lung adenocarcinomas but to an unknown end." (PMID 27933110, 2016). "Moreover, this work has identified several novel recurrent mutations in genes not typically associated with lung adenocarcinoma, which are each present in a significant subset of TCGA lung adenocarcinoma patients (e.g. IL32, LOC650368, HSD17B7P2 and RPSA)." (PMID 27933110, 2016).
myelodysplastic syndrome (1 paper, 2020). A clonal hematopoietic disorder characterized by dysplasia and ineffective hematopoiesis in one or more of the hematopoietic cell lines. "Prominent examples are RPS14/uS11, RPSA/uS2 and RPL38/eL38 genes with mutations associated with 5q- myelodysplastic syndrome, isolated congenital asplenia and skeletal defects during embryogenesis, including perturbations in the formation of the axial skeleton." (PMID 33575632, 2020).
myeloproliferative neoplasm (1 paper, 2012). A clonal hematopoietic stem cell disorder, characterized by proliferation in the bone marrow of one or more of the myeloid (i.e., granulocytic, erythroid, megakaryocytic, and mast cell) lineages. "It is also important to note that Hsp90, SET, RPSA have all been implicated in myeloproliferative neoplasms." (PMID 22723854, 2012). "Hsp90 is a therapeutic target in JAK2-dependent myeloproliferative neoplasms, RPSA is highly expressed in Acute Myeloid Leukaemia (AML) and SET expression is induced in Chronic Myelogenous Leukemia (CML)." (PMID 22723854, 2012).
Obesity (1 paper, 2010). Accumulation of substantial excess body fat. "In addition, it has been shown that binding of green tea catechin EGCG to RPSA causes anti-thrombotic, anti-allergic and anti-obesity effects and mediates cancer prevention by inhibiting cell growth, thus RPSA is a target in new therapies against this large group of diseases." (PMID 20233419, 2010).
ovarian tumor (1 paper, 2024). "Additionally, the expression levels of HSPA8 and SOD1 were higher in high-grade serous ovarian cancer samples compared to non-malignant ovarian tumor tissues, while RPL13A, PSMA5, and RPSA showed the opposite trend." (PMID 38166541, 2024).
pancreatic adenocarcinoma (1 paper, 2020). "Previous experiments from our laboratory identified RPSA as AG-9 receptor on HT-1080 human fibrosarcoma cell surface, and on MIA PaCa-2 cell pancreatic adenocarcinoma cells." (PMID 33396696, 2020).
Parkinson disease (1 paper, 2024). A progressive degenerative disorder of the central nervous system characterized by loss of dopamine producing neurons in the substantia nigra and the presence of Lewy bodies in the substantia nigra and locus coeruleus. "The association with the MAPT (H1c clade) and RPSA-MOBP loci may suggest common genetic pleiotropy across FTD and progressive supranuclear palsy (PSP) (MAPT and RPSA-MOBP loci) and across FTD, AD, Parkinson disease (PD), and cortico-basal degeneration (CBD) (MAPT locus)." (PMID 38889728, 2024).
Right ventricular cardiomyopathy (1 paper, 2024). Right ventricular dysfunction (global or regional) with functional and morphological right ventricular abnormalities, with or without left ventricular disease. "A spontaneously occurring mutation in Rpsa in a mouse line resulted in arrhythmogenic right ventricular cardiomyopathy, which was ascribed to nuclear functions of RPSA and binding to heterochromatin protein 1, suggesting that this gene may have a specific function in the heart." (PMID 38743494, 2024).
sarcoidosis (1 paper, 2017). Sarcoidosis is a multisystemic disorder of unknown cause characterized by the formation of immune granulomas in involved organs. "Additionally, both RPSA and RPL10A genes encoding ribosomal proteins were found to be significantly downregulated in sarcoidosis monocytes as compared to healthy monocytes." (PMID 28577019, 2017).
sporadic CJD (1 paper, 2011). "In order to find association of RPSA with sporadic CJD, we screened sequence of the RPSA in all available samples of sporadic CJD patients from Korean populations and investigated SNPs in the LRP/LR gene." (PMID 21838916, 2011). "Nevertheless, this study is important in that it forms the foundation of genetic association study on RPSA gene and sporadic CJD." (PMID 21838916, 2011). "To identify an association between RPSA polymorphisms and sporadic CJD, we screened nucleotide variations in RPSA using direct gene sequence or RFLP analysis." (PMID 21838916, 2011). "This was the first genetic association study of the polymorphisms of RPSA gene with sporadic CJD." (PMID 21838916, 2011). "Therefore, we investigated polymorphisms of human RPSA, and studied whether these polymorphisms are related to susceptibility to sporadic CJD." (PMID 21838916, 2011). "Although RPSA alone is not a disease-modifying gene for sporadic CJD in Koreans, these SNPs might have an effect on the expression or susceptibility of RPSA gene and PrPC-LRP-LR interaction." (PMID 21838916, 2011).
syphilis (1 paper, 2018). A contagious bacterial infection caused by the spirochete Treponema pallidum. "Inclusion of the tp0548 and rpsA subtyping methods allowed for greater discrimination of the yaws strains than the original CDC typing targets alone, similar to previous findings in syphilis." (PMID 30208094, 2018).